RN7SL435P (RNA, 7SL, cytoplasmic 435, pseudogene)
Gene: Miscellaneous RNA gene on chromosome 11 (59,291,052 to 59,291,333, reverse strand). Ensembl gene ENSG00000263944.
Homologues: Orthologues: chimpanzee Metazoa_SRP (99% identical), macaque Metazoa_SRP (92% identical). Paralogues in human: RN7SL1 (81% identical), RN7SL2 (80% identical), RN7SL3 (79% identical), RN7SL42P (79% identical), RN7SL18P (77% identical), RN7SL15P (77% identical), RN7SL732P (77% identical), RN7SL296P (77% identical), RN7SL126P (76% identical), RN7SL177P (76% identical), RN7SL357P (76% identical), RN7SL5P (76% identical), and 701 more.